CRP (C-reactive protein)
Diseases named in the same sentence as CRP in open-access papers (continued):
Sharing a sentence is not in itself a finding about the gene and the disease.
atherosclerosis (continued). "We reasoned that even if there was no acidic pH around injected mutant CRP in the available murine models, mutant CRP would be able to recognize and bind atherogenic LDL and exert a protective effect on the development of atherosclerosis." (PMID 32849641, 2020). "A CRP mutant, that is non-native CRP, which readily binds to atherogenic LDL, has been found to be atheroprotective in a murine model of atherosclerosis." (PMID 31379851, 2019). "The interaction of CRP with LDL and other factors in atherosclerosis has recently been reviewed, although without consideration of CRP isoforms." (PMID 27738646, 2016). "Consequently, the ApoE−/− mouse model may not be ideal for studies of human CRP in atherosclerosis." (PMID 24872599, 2014). "In our study, postprandial plasma CRP, but not haptoglobin, IL-6 or TNF-α, positively correlated with the severity of beginning atherosclerosis." (PMID 21756316, 2011). "C-reactive protein (CRP), a sensitive, but nonspecific marker of inflammation has been shown to play proatherogenic roles in the process of atherosclerosis." (PMID 19624831, 2009). "General inflammation manifested by an increase in the level of C-reactive protein (CRP) and the decrease in complement C3c and C4 levels also does not intensify the progression of atherosclerosis in young people if only CRP does not permanently increase to at least 20 mg/l." (PMID 36622519, 2023). "The results of this study demonstrated that serum uOC level had a significant negative correlation with CRP level, indicating that the microinflammatory condition in CKD patients might be involved in the development of atherosclerosis." (PMID 26381729, 2015). "We conclude that apoB and CRP, but not LDL-cholesterol predicted subclinical atherosclerosis." (PMID 23536999, 2013). "Psoriasis vulgaris patients with atherosclerosis had higher levels of hs-CRP (median = 1.22; interquartile range—IQR = 0.34–12.11) and IL-17A (median = 1.30; IQR = 0.43–4.28), but a lower level of TNF-α (median = 0.54; IQR = 0.13–3.41) compared to those without atherosclerosis (p < 0.05)." (PMID 39104857, 2024). "They found that CRP mediated the uptake of native LDL without a need for biochemical modification of LDL via CD32, the major CRP receptor on human macrophages, suggesting that CRP binding to LDL in human arterial wall links LDL deposition to the onset of atherosclerosis." (PMID 27633999, 2016). "Moreover, inflammation may not drive all transitions from stable atherosclerosis to acute thrombotic events, as demonstrated in studies showing that about half of ACS occurred in the presence of normal levels of C-reactive protein (CRP), a marker of inflammation." (PMID 33918214, 2021).
Stroke (1,207 papers, 2004 to 2026). Sudden impairment of blood flow to a part of the brain due to occlusion or rupture of an artery to the brain. "In parallel, CRP has been observed to co-localize with Aβ plaques in postmortem studies and promote microglial activation, which is associated with stroke and AD neuroinflammation." (PMID 41517237, 2026). "In stroke patients, elevated levels of CRP are considered one of the important biomarkers associated with disease severity, prognosis, and the risk of complications." (PMID 41432712, 2026). "Dysphagia and elevated CRP are early markers of emergence of stroke-associated pneumonia, whereas leukocyte count and temperature show limited forewarning value." (PMID 41782813, 2026). "IL‐6 associated with approximately 19% higher stroke risk per SD increase; hs‐CRP independently predicts events." (PMID 41567175, 2026). "CRP and PCT have been identified as independent risk factors influencing pulmonary infections in stroke patients, and elevated levels of CRP are considered a significant risk factor for mortality in elderly patients with SAP." (PMID 40098935, 2025). "Elevated CRP levels are linked to higher risks of heart attack, stroke, and other cardiovascular events, either independently or with others." (PMID 39940273, 2025). "Apart from NIHSS at admission, only atrial fibrillation was significantly associated with CRP (48–72 h after stroke) in the preceding univariate step for the multivariate analysis." (PMID 40447994, 2025). "While ALB showed a robust protective impact in hypertensive people, with greater ALB levels linked to a decreased risk of stroke (OR 0.50, 95% CI 0.37–0.68), we also discovered a positive correlation between CRP and stroke risk (OR 1.13, 95% CI 1.04–1.22)." (PMID 40491586, 2025). "Three latent profiles of psychoneurological symptom clusters exist in patients with a first stroke and are associated with markers of inflammation (interleukin-6 and hypersensitive C-reactive protein), thereby affecting their quality of life." (PMID 40709232, 2025). "We chose WBC for this experimental analysis since we found CRP and body temperature was correlated to expected risk factors such as stroke severity or type." (PMID 40447994, 2025). "The results indicate that BMI, HBP, SBP, CRP, stroke, and renal insufficiency are associated with DR." (PMID 41340073, 2025). "In RA, elevated CRP levels are correlated with an increased risk of cardiovascular incidents, particularly HF, myocardial infarction, CV mortality, and stroke, increasing by 14% for each mg/L of CRP." (PMID 40283183, 2025). "Persistently elevated CRP during hospitalization (for example, after thrombolysis) has been linked to poor recovery, even in patients with initially mild strokes." (PMID 40869247, 2025). "Elevated CRP levels are associated with poor outcomes in stroke patients and reflect the systemic inflammatory state." (PMID 40066310, 2025). "Elevated levels of Hcy and CRP are also linked to worse neurological outcomes, as measured by the National Institutes of Health Stroke Scale (NIHSS)." (PMID 39898976, 2025). "In summary, both IL-6 and CRP are inflammatory biomarkers with significant predictive value for the risk of recurrent vascular events after stroke." (PMID 40217803, 2025). "Elevated CRP levels during the subacute phase have been consistently linked with increased mortality, risk of stroke recurrence, and poor functional recovery." (PMID 40869247, 2025). "Elevated levels of AIP and hs-CRP were independently and jointly associated with an increased risk of cardiovascular disease, particularly stroke." (PMID 40842496, 2025). "The Women's Health Study established that high-sensitivity CRP (hs-CRP) levels above the normal range are directly linked to heart attacks and strokes while ignoring LDL-C measurements." (PMID 41431526, 2025).
Stroke (continued). "This particularly applies to pro-inflammatory cytokines responsible for inducing, mainly in the liver, the fibrinogen and c-reactive protein (CRP), a standard inflammation marker associated with stroke." (PMID 40305179, 2025). "A relevant meta-analysis showed that CRP levels were significantly increased in the acute phase of ischaemic stroke, increasing the risk of dementia in the later phase of stroke." (PMID 40779499, 2025). "For example, elevated CRP levels are associated with a higher risk of myocardial infarction and stroke." (PMID 40438231, 2025). "The association persisted in the fully adjusted model (Model 4), which accounted for laboratory indicators including CRP and Cr, showing a 149% higher risk of incident stroke (HR = 2.49, 95% CI: 1.69–3.65)." (PMID 40988399, 2025). "High-sensitivity C-reactive protein (hs-CRP), fibrinogen, and D-dimer are increasingly studied as potential markers of stroke risk, reflecting underlying inflammation and coagulation abnormalities." (PMID 40217803, 2025). "In contrast, traditional inflammatory markers like high-sensitivity C-reactive protein (hs-CRP) exhibit limited sensitivity and specificity in comprehensively assessing and predicting stroke risk." (PMID 40823291, 2025). "The risk of both MI and stroke was higher for individuals with higher C-reactive protein (CRP) concentrations." (PMID 40132892, 2025). "CRP is known to be associated with an increased risk of stroke incidence, which highlights the link between systemic inflammation and stroke." (PMID 40584532, 2025). "The risks of CVD events (including heart disease and stroke) were significantly elevated among participants with AIP ≥ median or hs-CRP ≥ 1 mg/L, with these associations remaining significant across adjusted models." (PMID 40842496, 2025). "Patients with a CRP exceeding 300 mg/L had over four times the risk of MI and three times the risk of stroke compared with patients with CRP<100 mg/L." (PMID 40132892, 2025). "CHD, insular cortex lesions, peak NT-proBNP and CRP levels, and higher stroke severity (NIHSS score) are significant risk factors for myocardial injury in AIS patients with DM." (PMID 41541883, 2025). "Structural changes in the heart, such as altered left ventricular geometry, are linked to higher stroke recurrence rates, while elevated inflammatory markers, like high-sensitivity C-reactive protein, are associated with increased vascular events." (PMID 40296948, 2025). "METS-IR and UA levels were positively associated with an increased risk of stroke onset, and CRP mediated these relationships." (PMID 39634177, 2024). "CRP has consistently been found to be associated with excess mortality in cardiovascular disease and stroke and is often linked specifically with CHF, aortic valve disease, and myocardial infarction." (PMID 39916950, 2024). "This prediction model incorporates variables such as age, C-reactive protein, serum phosphorus, BMI, and mid-upper arm muscle circumference, thus offering a multidimensional risk assessment for sarcopenia in post-stroke patients." (PMID 39717682, 2024). "In the study of the relationship between CRP levels and stroke, it was found that higher CRP levels in Chinese women are associated with an increased risk of stroke, with a risk 2.13 times higher than that of the normal population." (PMID 39247228, 2024). "High levels of oxLDL and high-sensitivity C-reactive protein (CRP), when combined, are associated with increased risk of recurrent stroke, combined vascular events, and poor functional outcome in patients with minor stroke or transient ischemic attack." (PMID 39713216, 2024). "Secondly, the study’s cross-sectional design inherently restricts the ability to establish causality between the observed biomarker levels (HDL, CRP, and ferritin) and stroke outcomes." (PMID 39258059, 2024).
Stroke (continued). "In this study, we demonstrated that elevated WBC or CRP levels combined with low eGFR were associated with highest risk of post-stroke pneumonia and unfavorable at-discharge functional outcome in AIS patients after IVT." (PMID 39736651, 2024). "In patients with ischemic stroke, CRP level during the hospital stay is reported as an independent risk factor for poor functional recovery, post-stroke depressive symptoms, and mortality." (PMID 39063013, 2024). "Elevated CRP levels, linked to an increased risk of neurodegenerative diseases and stroke, underscore the broader implications of metal exposure in systemic inflammation." (PMID 39267632, 2024). "Using bivariate correlation analysis, we confirmed that NSE on admission and S100-β level at 48 h of stroke onset was significantly associated with hs-CRP and D-D, respectively." (PMID 39669377, 2024). "In patients with recent lacunar stroke, high sensitivity C-reactive protein (hsCRP) levels predict the risk of recurrent stroke and other vascular events." (PMID 39758197, 2024). "Mendelian studies have shown a significant causal relationship between CRP and hypertensive heart disease, which is a significant risk factor for stroke." (PMID 39634177, 2024). "Of note, the different CRP levels on admission suit well into the ongoing debate of an underlying pro-inflammatory process as a contributing factor for stroke ictus." (PMID 38750601, 2024). "Elevated CRP levels are predictive of stroke risk and poorer outcomes, reflecting the degree of inflammation." (PMID 39258059, 2024). "Elevated levels of C-reactive protein (CRP) have been associated with poorer outcomes following ischemic attacks, significantly heightening the risk of subsequent strokes." (PMID 39099996, 2024). "Two studies indicate a strong association of poor outcomes with high sensitivity (hs)-CRP measurements at 24–48 h and 7 days post-stroke, reflecting impairment of the recovery process due to prolonged inflammation after ischemic stroke." (PMID 39091979, 2024). "Many prospective studies have shown that plasma CRP is a strong independent predictor of the risk of acute myocardial infarction, stroke, peripheral arterial disease, and vascular death." (PMID 39588387, 2024). "C-reactive protein mediated the association between sedentary behavior and stroke among older adults, with a mediation of 3.64%." (PMID 39758197, 2024). "Lower levels of CRP have been associated with a cognitive impairment in stroke patients developing dementia after ischemia." (PMID 39610697, 2024). "In conclusion, we found that METS-IR and UA levels were positively associated with an increased risk of stroke onset, and that CRP mediated these relationships." (PMID 39634177, 2024). "C-reactive protein mediated the association between sedentary behavior and stroke in older adults with a mediator ratio of 3.64%." (PMID 39758197, 2024). "The first point is that GPS uses only two serum parameters [albumin and C-reactive protein (CRP)] to predict outcomes, but the risk of stroke in these patients is multicausal." (PMID 39292095, 2024). "A recent systematic review with data from 3,536 stroke patients from 13 cohort studies (12 Chinese, 1 European) demonstrated that higher CRP levels in the acute phase of stroke indicate a higher risk for PSD during follow-up of one year." (PMID 37848651, 2024). "The European prospective investigation into cancer and nutrition (EPIC)-Norfolk cohort-based study included 18,450 healthy individuals at baseline, and the results showed that CRP was associated with the occurrence of a stroke." (PMID 39247228, 2024). "In stroke patients, C-reactive protein (CRP) has emerged as a critical component linked to the risk of subsequent cardiovascular events." (PMID 38310557, 2024). "This can be explained by the fact that METS-IR and UA levels can directly affect the risk of stroke occurrence and can also indirectly affect the risk of stroke by affecting CRP levels." (PMID 39634177, 2024).
Stroke (continued). "The linkage between CRP and stroke outcomes extends into the genetic realm, with variations within the CRP gene implicated in stroke vulnerability and prognoses." (PMID 38377025, 2024). "At the same time, Serum C reactive protein (CRP) is a marker of systemic inflammation and is associated with an increased risk of stroke and unstable carotid atherosclerotic plaques." (PMID 38434202, 2024). "Studies have identified inflammatory markers like CRP, IL-6, and IL-33 as predictors of initial stroke risk and post-stroke prognosis." (PMID 38169754, 2024). "In people aged 60 years and older, sedentary behavior was positively associated with stroke, whereas physical activity was negatively associated with stroke, and C-reactive protein mediated the relationship between sedentary behavior and stroke." (PMID 39758197, 2024). "CRP (C-reactive protein): This protein is released in response to inflammation in the body and can be used to detect the risk of stroke." (PMID 40777969, 2024). "Proportion of association of per SD of LDH or hs-CRP with 90-day mRS mediated by follow-up stroke recurrence." (PMID 39280700, 2024). "Measuring CRP levels can aid in assessing stroke risk and guiding treatment decisions, highlighting its importance as both a biomarker and therapeutic target for better stroke management and prevention." (PMID 39258059, 2024). "Detailed genetic analyses have identified a significant correlation of rs3093059 and rs3091244 polymorphisms with ischemic stroke, underscoring the CRP gene's role in stroke susceptibility." (PMID 38377025, 2024). "Positive correlation between LDH and hs-CRP was found and mediation effects of stroke recurrence in the association between LDH or hs-CRP and functional disability were both less than 20%." (PMID 39280700, 2024). "A human study has shown that stroke patients have increased valeric acid in their feces and this increase was associated with increased white blood cells and high sensitive C-reactive protein in the blood." (PMID 37697393, 2023). "Canakinumab, an anti-inflammatory drug, has been shown to significantly reduce the risk of recurrent cardiovascular events, including stroke, in patients with a history of myocardial infarction and elevated levels of hs-CRP." (PMID 37342777, 2023). "The 3-month mortality was similar between the two groups (both LT and KT, 10.3%) and was independently associated with in-hospital stroke and elevated C-reactive protein." (PMID 37034098, 2023). "In this study, only CRP levels of > 3 mg/L were associated with new onset ischemic heart disease, potentially representing the pre-stroke atherothrombotic burden and vascular inflammation." (PMID 37119383, 2023). "To investigate the association of CRP levels with cardiac complications or death after stroke in the elderly, we performed a sensitivity analysis including only > 65 years old." (PMID 37119383, 2023). "Levels of CRP were found to be associated with the risk of incident dementia (HR 0.95, 95% CI: 0.91–0.99, p = 0.029), stroke (HR 1.04, 95% CI: 1.01–1.07, p = 0.005) and MDD (HR 1.06, 95% CI: 1.03–1.08, p < 0.001)." (PMID 38071240, 2023). "This is the first study to provide evidence of an association between elevated CRP levels during the first 24 h after stroke 30-day cardiac complications/death." (PMID 37119383, 2023). "Hs-CRP levels are strongly associated with mortality, risk of stroke recurrence and poor prognosis in stroke patients." (PMID 37342777, 2023). "By increasing the risk of recurrent stroke, elevated hs-CRP levels are associated with the death of patients after stroke, strengthening the significance of hs-CRP levels in predicting mortality." (PMID 37342777, 2023). "Elevated blood concentrations of CRP have been linked to subsequent risk of coronary heart disease, stroke, and vascular mortality." (PMID 36831896, 2023).